LINC01485 (long independently transcribed non-coding RNA 1485)
Gene: Long non-coding RNA gene on chromosome 5 (173,778,527 to 173,809,039, reverse strand). Ensembl gene ENSG00000254211.
Diseases named in the same sentence as LINC01485 in open-access papers:
LINC01485 is named in the same sentence as 2 diseases in open-access papers, as found by Europe PMC text mining. Sharing a sentence is not in itself a finding about the gene and the disease. The quoted sentences say what the papers report.
gastric cancer (1 paper, 2024). A primary or metastatic malignant neoplasm involving the stomach. "LncRNAs, especially the cytoplasmic lncRNA LINC01485, have been identified as actively involved in gastric cancer development." (PMID 39130630, 2024). "LINC01485 plays a role in gastric cancer progression by promoting tumor cell growth and migration." (PMID 39130630, 2024).
tumor (1 paper, 2025). "In CRC, LINC01485 is upregulated and promotes tumor cell proliferation, migration, invasion, and in vivo growth, by acting as a ceRNA for miR-383-5p." (PMID 40647481, 2025).